IFITM1 (interferon induced transmembrane protein 1)
Diseases named in the same sentence as IFITM1 in open-access papers (continued):
Sharing a sentence is not in itself a finding about the gene and the disease.
infection (continued). "Mouse embryo fibroblasts derived from a knockout strain lacking all IFITM genes (IFITM1, 2, 3, 5 and 6) were more susceptible to infection compared to their wild-type counterparts." (PMID 21994648, 2010). "Thus, it was thought that IFITM1 is not a major host factor associated with the γ-IFN-mediated restriction of HIV-1-based vector infection." (PMID 35883685, 2022). "However, our human and mice analyses might indicate a direct influence of infection on the regulation of bulk IFITM1 and IFITM3 expression in vivo." (PMID 35708622, 2022). "It is thus possible that the superiority of HIV-1NL4–3 over HIV-1BH10 in replicating in IFITM1-expression SupT1 cells, despite that both viruses are equally impaired by IFITM1 in the one-round infection, might be a result of the greater ability of HIV-1NL4–3 to transmit between cells." (PMID 25738301, 2015). "To assess the antiviral protection conferred by endogenous IFITM1 and IFITM3 against viruses fusing at endolysosomal membranes, we measured cellular infection by influenza A virus." (PMID 42262132, 2026). "For this purpose, PBE cells were challenged with SIV H1N1 or H3N2 and the expression of IFN-β and the antiviral factors Mx1, Mx2, IFITM1, OAS1, OAS2, and OASL were evaluated at different hours post-infection." (PMID 40565228, 2025). "At h 36, the infection with SIV H1N1 (MOI 0.01) induced increases of approximately 20-, 70-, 30-, and 5-fold in IFN-β, Mx1, Mx2, and IFITM1, respectively, while these changes were 90-, 250-, 300-, and 25-fold for SIV H3N2 (MOI 0.01)." (PMID 40565228, 2025). "For instance, Hussein and Sakula recently highlighted that overexpressing IFITM1 can enhance the infection of target cells by KSHV, whereas silencing IFITM1 results in reduced infection rates." (PMID 40416980, 2025). "For example, both IFITM1 and IFITM3 can modestly promote the infection of various cell types by human papillomavirus 16 (HPV-16)." (PMID 40416980, 2025). "Increased infection was also observed for IFITM3 KO HAP1 fibroblasts and for IFITM1/2/3 KO HeLa cells." (PMID 39477971, 2024). "Key regulatory genes such as IFI16, IFITM1, and SP100 show exceptionally high degrees of connectivity, indicating their central role in the immediate host response to the infection." (PMID 39591472, 2024). "Interferon-regulated genes such as Ifitm1 and Ifitm330 were notably induced among serous cells during the early injury/inflammatory phase of PR8 infection, thus presumably providing a survival advantage to this pool of airway progenitors." (PMID 37726288, 2023). "Shared genes upregulated with a higher log2 fold change in B/Victoria infection included known anti-viral proteins IFIT1-3, IFITM1, MX2, IFI44L and ISG15 along with mitochondrial-related gene CMPK2." (PMID 37766362, 2023). "Our results showed that overexpression of IFITM1, IFITM2, IFITM3, or LY6E significantly inhibited the infection of CCoV-HuPn-2018pp and HCoV-229Epp." (PMID 37676001, 2023). "Others have also reported that IFITM1 and IFITM3 have a different tissue-specific expression pattern during H9N2 infection in BALB/c mice (Yu and others 2015)." (PMID 35708622, 2022). "To test the link between infection enhancement and downmodulation of IFITM proteins by rapalogs, we probed for levels of IFITM3, IFITM2, and IFITM1 by immunoblotting whole cell lysates using specific antibodies." (PMID 33880473, 2022). "Infections with both EHI0418Y05 and EHI0169Y07 elicited a significant rise in IFN-β transcript (p ≤ 0.001), but IFN-stimulated genes, IFITM1, RSAD2, and ISG15, were expressed at higher levels following infection with EHI0418Y05 than with EHI0169Y07." (PMID 35208767, 2022).
infection (continued). "In the peripheral blood lymphocytes of ARV-infected SPF chickens, type I IFN (IFN-α, IFN-β), type II IFN (IFN-γ), and ISGs (Mx, IFITM1, and OAS) were all upregulated in the early stage of infection, with their expression peaking at 3 days after infection." (PMID 36187980, 2022). "In contrast, all these genes were strongly induced in peritubular cells 72h post-infection with ZIKV, except for IFITM1." (PMID 35784373, 2022). "Four strains with the highest viral copy numbers (n = 4) and three strains with the lowest viral copy numbers (n = 3) were selected to evaluate TNF-α, IL-6, IFN-β, ISG-15, IFITM1, and TRIM22 expression levels at 6 h post-infection." (PMID 36146585, 2022). "Although IFITM1/2/3 knockout enhanced KSHV and RRV infection in A549 cells and HFF, the overall contribution to the IFN-mediated block to infection was different." (PMID 34933450, 2021). "More specifically, IFITM1—interferon-induced transmembrane protein 1, IL21R—interleukin 21 receptor and IFITM3—the interferon-induced transmembrane protein 3 (IFITM3), were overexpressed, as observed after infection with precHP viruses." (PMID 34835129, 2021). "We showed that the expression of placental IFITM1 and IFITM3 transcripts was upregulated in women with severe infection when compared to women with asymptomatic/mild disease or to negative controls." (PMID 34257394, 2021). "Of note, we observed that several duck IFN-stimulated genes (ISGs), including IFI35, Mx, ISG15, ZC3HAV1, LGP2, IFITM1, IFITM2, and Viperin, were dramatically upregulated upon DTMUV infection." (PMID 34335626, 2021). "Both IFITM1 and IFITM3 were upregulated in the sampled tissues after DTMUV infection, especially the cecum and cecal tonsil, where DTMUV was intensively located, indicating that DTMUV is responsible for the high expression levels of goose IFITM1 and IFITM3." (PMID 32641107, 2020). "This included IFITM1 and IFITM2, which are known to inhibit the infection and replication of respiratory syncytial virus, IFI27, a known biomarker for RSV29, and IRF7, a gene associated with suppression of innate immunity response." (PMID 31554845, 2019). "After 44 h, the level of HSV infection (MOI of 0.01) in IFITM1-expressing A549 cells was 36.6%, compared to 75.5% and 58.1% for IFITM2 and IFITM3, respectively, and 75.1% infection of control empty vector-transduced cells." (PMID 30567988, 2019). "Using DF-1 cell system, we found that knockdown of endogenous IFITM1 and IFITM3 by short hairpin RNA (shRNA) markedly enhanced ATMUV infection in host." (PMID 28473814, 2017). "In agreement, we also see that both IFITM1 and IFITM3 can inhibit infection by SFV, when virus is fused at the cell surface." (PMID 27219333, 2016). "Considering that IFITM1 and IFITM3 regulate permeability of the cell membrane, it is plausible that SPTA1 is also involved in aiding the host cell’s architecture to impede infection." (PMID 29333229, 2016). "Antiviral genes, including IFNA, IFNG, MX1, IFITM1, IFITM3, and IFITM5, were upregulated in response to infection." (PMID 25505077, 2015). "We also observed colocalization of endogenous IFITM1 and dsRNA in AiV-infected cells at 2.5 h post-infection but not at 4 h post-infection, suggesting that endogenous IFITM1 localizes to viral replication sites early in infection." (PMID 37252940, 2023). "Herein, we observed no significant change in the mRNA expression profiles of the antiviral ISGs MX1 and IFITM1 during secondary H3N2 infection nor HRV-A16 re-infection as compared to their respective single infections in hNECs." (PMID 37190061, 2023). "We also validated the significant elevation in the baseline protein expression of MX1 and IFITM1 after 14 days of prolonged primary HRV infection (even without sequential infection of hNECs)." (PMID 37190061, 2023).
infection (continued). "Interestingly, however, the protein expression levels of MX1 and IFITM1 during secondary H3N2 infection and HRV-A16 re-infection were significantly increased as compared to their respective single infections." (PMID 37190061, 2023). "Consistent with previous reports, expression of plasma membrane resident IFITM1 did not inhibit infection by these viruses that enter through low pH endosomal compartments." (PMID 34981045, 2021). "Of note, an effect of IFITM1 on KSHV infection has already been described by Hussein and Akula; however, in contrast to our study, their study reported that infection by KSHV, EBV, and HSV-2 was enhanced upon overexpression of IFITM1 in the BJAB B-cell line and in HMVEC-D cells." (PMID 34933450, 2021). "Our previous study showed that expression levels of type I IFNs, including IFNA and IFNB, type II IFN IFN-γ, and the ISGs MX, IFITM1, and OSAL were all upregulated in peripheral-blood lymphocytes of SPF chickens in the early stage of ARV infection and peaked 3 days after infection." (PMID 33614762, 2021). "This suggests that lncR 8 negatively regulates Mx1 and IFITM1 during HCV replication and infection." (PMID 31200545, 2019). "The binding assay performed on BJAB cells demonstrated that the transfection of cells with (NS)siRNA or siRNA specific to IFITM1 did not block 10 multiplicity of infection (MOI) of KSHV and EBV from binding the target cells." (PMID 30237526, 2018). "The late endosomal IFITM2 is less restrictive and the plasma membrane IFITM1 does not inhibit normal infection by either virus." (PMID 27219333, 2016). "Novel PPIs of IFITM1 and IFITM3 shed light on possible mechanisms of host invasion adopted by Zika virus including suppression of the immune system and cognitive and birth defects following infection." (PMID 29333229, 2016). "Our data confirm that infection with hrHPV decreases basal STAT1 protein levels in KCs but also show that hrHPV does not interfere with IFNγ-induced STAT1 activation per se, as reflected by STAT1 phosphorylation and increase in RARRES1 and IFITM1 expression." (PMID 27920775, 2016). "We therefore examined gene expression for several important interferon-related genes (IFNα2, IFNα4, IFNβ, IFNαβR, IFNγ, IFNγR, Irf3, Irf7, Mx1, Oas1, IFITM1, IFITM2), along with inflammasome-related genes IL-1β and NLRP3, and chemokines CCL5, CCL7, and CCL12 at d1 post-infection." (PMID 26110868, 2015). "With the insertion of K1L and C7L, this response was tempered; infection with NYVAC-C-KC-ΔB8RΔB19R induced increased transcriptional levels of seven of the genes shown, relative to NYVAC-C-KC (IFI35, IFI44, IFI44L, IFIT1, IFIT3, IFITM1, and IFITM2)." (PMID 22096477, 2011). "However, combined knockdown of both IFITM1 and IFITM3 led to even greater infection." (PMID 42262132, 2026). "It is notable however, that although GBPs did not sensitize to IFITMs, combining GBP5 in producer cells with IFITM1 in target cells led to an almost complete inhibition of Wuhan-Hu-1 infection when compared with infection in the absence of these restriction factors." (PMID 36693093, 2023). "Furthermore, while temsirolimus significantly promoted infection by 10-fold in WT cells, little to no enhancement was observed in IFITM1–3 KO cells." (PMID 33880473, 2022). "While we did not observe this phenomenon in the cells analyzed in this study, our observations of cell-specific antiviral activity do not rule out the possibility that in some cells infection might actually be enhanced by IFITM1 expression." (PMID 34933450, 2021). "MLV-LP infection of HFF was not significantly affected by IFITM1/2/3 knockout." (PMID 34933450, 2021). "If that is the case, how can IFITM1 enhance infection of not just KSHV; but also of EBV and HSV-2?" (PMID 29269892, 2017). "Indeed, disruption of endogenous IFITM1 and IFITM3 by shRNA greatly enhanced ATMUV infection." (PMID 28473814, 2017).
infection (continued). "Furthermore, a mutant of IFITM3, which is localized to the plasma membrane (Y20A), inhibited infection by plasma membrane fusion more potently than IFITM1, but did not inhibit the endosomal route of infection." (PMID 27219333, 2016). "Moreover, IFITM1, 2 and 3 did not inhibit infection by two other DNA viruses, human cytomegalovirus (HCMV) and adenovirus type 5 (Ad5)." (PMID 24827144, 2014). "Interestingly, although SARS-CoV and HCoV-NL63 share the ACE2 receptor for infection of host cells, deletion of the C-terminal 3, 6, or 9 amino acids did not apparently affect the activity of IFITM1 to inhibit SARS-CoV entry but enhanced the activity of IFITM1 to inhibit the entry of HCoV-NL63." (PMID 30687247, 2018). "The results showed that the expression of porcine IFITM1 or IFITM1-HA protein, but not IFITM2/3, significantly increased the infection of cells by PEDV-HM." (PMID 40353666, 2025). "We recently utilised a doxycycline (DOX)-inducible protein overexpression system in A549 airway epithelial cells to demonstrate that IFITM1, IFITM2, and IFITM3 are cellular host factors that inhibit IAV but not parainfluenza virus (PIV)-3 infection." (PMID 37111405, 2023). "IAV-LP infection was increased upon IFITM1/2/3 knockout, while MLV-LP infection was not affected by IFITM1/2/3 knockout in A549 cells, in keeping with published results." (PMID 34933450, 2021). "In agreement with the results in IFITM1/2/3 knockout experiments and published results, IAV-LP infection was reduced by all IFITMs, most prominently by IFITM3, and infection of MLV-LP was not affected." (PMID 34933450, 2021). "These top genes included IFITM1 and IFITM2, which were significantly expressed between the acute and post-acute visit, but not between infants with severe versus mild infection, and CCR7, which has been found to be downregulated in RSV patients." (PMID 31554845, 2019). "We show that normal infection by both SFV and SINV is restricted by IFITM3 and, to a lesser extent, by IFITM2, but not by IFITM1." (PMID 27219333, 2016). "Similar defects were also observed for HIV-1NL4–3 infection of IFITM1-expressing SupT1 cells, which indicates that HIV-1NL4–3 escapes IFITM1 in the spread infection without the need to restore this decrease in Gag/p24 expression." (PMID 25738301, 2015). "We suggest that IFITM1, unlike IFITM2 and IFITM3, primarily functions through alteration of the plasma membrane and, as such, is able to restrict viruses at this initial point in infection." (PMID 30567988, 2019). "Additionally, we demonstrate that IFITM1, 2 and 3 did not inhibit infection of two other DNA viruses, Ad5 and HCMV, whereas infection of SARS-CoV, a positive control, was broadly restricted." (PMID 24827144, 2014). "However, the majority of antiviral ISGs, including OAS1, MX2, IFI6, IFITM1, IFI27, and IFTM2, were downregulated in cells transduced with MyD88 (in the presence or absence of infection) and were also downregulated in cells infected with UL88-deficient HCMV vs wild-type HCMV." (PMID 40638072, 2025). "It is not yet clear whether IFITM1 regulates DNA virus (e.g., HBV) infection mediated by ABHD16A." (PMID 40434075, 2025).
tumor (75 papers, 2009 to 2026). "Changes in CD40 and CD166 membrane levels were found to be associated with their respective expression data, confirming that IFITM1 plays a significant role in regulating genes associated with tumor progression." (PMID 40314078, 2025). "In this study, we found that IFITM1 was downregulated in MPNST tumor tissue samples from patients with NF1 and NF1-associated MPNST Schwann cell lines." (PMID 39273214, 2024). "Analysis of scRNA-seq TNBC data further supported the significant association between MUC1 and expression of IRDS genes encoding IRF7, BST2, IFI35 and IFITM1 in individual TNBC tumor cells." (PMID 35681561, 2022). "Current knowledge of the molecular mechanism by which IFITM3 confers migration and metastasis benefits to tumor cells shows partial overlap with pathways linked to IFITM1." (PMID 36466909, 2022). "The association between IFITM1 and immune cell infiltrations was further assessed using the ssGSEA and Tumor Immunity Estimation Resource (TIMER)." (PMID 36591519, 2022). "In order to explore the underlining mechanisms, we found the role of IFITM1 has been shown in the tumorigenesis involving tumor cells unlimited proliferation, invasion, angiogenesis, metastasis, and treatment resistance." (PMID 33869009, 2021). "More recently, IFITM1 has also been implicated in tumorigenesis and there is evidence that it can positively or negatively regulate cell proliferation depending on the tumor cell type." (PMID 25588716, 2015). "The effect of IFITM1 on tumor progression is often linked to altered levels of β-catenin, cyclin D1 and c-myc, which might account for the roles of IFITM1 in cancer cell migration, metastatic potential and proliferation." (PMID 36466909, 2022). "Aberrant expression of IFITM1 promotes tumor cell proliferation, inhibits cell death, stimulates invasion and metastasis, contributes to cancer cell resistance to endocrine therapy, chemotherapy and radiotherapy, and has prognostic value for patient outcomes." (PMID 40314078, 2025). "Basal expression of IFITM1 was examined in tumor tissues obtained via surgical resection of six patients with NF1 at Ajou University Hospital." (PMID 39273214, 2024). "Studies showing the positive role of IFITM1 in tumor progression have mainly used epithelial cells and fibroblasts." (PMID 39273214, 2024). "To validate this finding at the protein level, we stained pretreatment tumor samples of the whole cohort (n = 130) for IFITM1." (PMID 38653773, 2024). "The upregulation of OAS1, OAS3, and IFITM1 expression in various tumor cell lines is observed following multi-fraction irradiation." (PMID 38473966, 2024). "Collectively, these results suggest that IFN-γ treatment suppresses tumor progression through induction of IFITM1 expression and subsequent inhibition of Ras and ERK1/2 activation." (PMID 39273214, 2024). "In conclusion, we have described a case of CCSTL with the presence of the characteristic YAP1-TFE3 fusion and have expanded the knowledge about the morphological features of this tumor by the presence of multinucleated giant cells and IHC expression of IFITM1." (PMID 36707859, 2023). "Comparing the primary tumor with one of the spinal lesions, eight genes were differentially expressed, with IFITM1 and ZFHX4 being notable due to their described roles in cancer metastasis." (PMID 36937401, 2023). "An in vivo experiment using a xenograft tumor Balb/c mouse model showed that IFITM1 knockdown in combination with irradiation resulted in distinct tumor suppression compared to irradiation alone." (PMID 36466909, 2022). "Of the six genes identified, IFI27, IFI6, IFITM1, ISG15, and BST2 have been reported to be associated with cancer cell proliferation and tumor growth." (PMID 35267998, 2022). "IFITM1 is the main IFITM family member reported in tumor progression and poor prognosis for many human cancer types." (PMID 36008984, 2022).